CD70 (CD70 molecule)
Diseases named in the same sentence as CD70 in open-access papers (continued):
Sharing a sentence is not in itself a finding about the gene and the disease.
tumor (continued). "Regardless, there was recognizable consistency in the positive outcomes that the killing effect of nb70CAR-T depended on the CD70 expression level of tumor cells." (PMID 36932256, 2023). "When delivered intravenously, CXCR1/2 modified CD70-CAR T-cells showed more remarkable CAR T-cell migration to the tumor site than their CD70-CAR T-cell-treated counterparts." (PMID 38136398, 2023). "Defucosylated anti-CD70 monoclonal antibody cusatuzumab (ARGX-110) prevents tumor immune escape by blocking the survival of Tregs and restoring normal myeloid differentiation." (PMID 37849799, 2023). "In tumor-bearing mice, this CD70 interacts constitutively with CD27+ Tregs during tumor development, thereby promoting Treg expansion and preventing cytotoxic T cell responses." (PMID 37545491, 2023). "Therapeutic inhibition of CD70 overcomes Treg immunosuppression, enhances anti-tumor immunity, and synergizes with PD-1 blockade in pre-clinical animal models." (PMID 37024479, 2023). "CD70 blocking in C666 cells showed comparable tumor-killing and cytotoxicity-enhancing effects with cusatuzumab treatment, further confirming CD70 inhibition is effective in inducing stronger anti-tumor immunity." (PMID 37024479, 2023). "We found that CD70-KO in C666 cells greatly enhanced cytotoxicity-dependent tumor cell death, preferentially in a co-culture system similar to the physiological T-cell landscape in NPC patients, with a higher expression of CD27 on CD4+ T cells." (PMID 37024479, 2023). "Unsupervised clustering of RNASeq data revealed two distinct transcriptional groups, that shared strong expression of CD70 and IL1R2, previously linked to tolerogenic tumor microenvironments." (PMID 37495858, 2023). "Here, we describe the first radiolabeled VHH targeting human CD70 that can be used to non-invasively and longitudinally assess CD70 positivity of tumor cells." (PMID 37093350, 2023). "On a different note, the tight regulation that governs co-stimulatory CD70/CD27 signaling can be aberrantly altered to have tumor-favoring consequences." (PMID 37345056, 2023). "Constitutive expression of CD70 on tumour cells has been documented in cancer in contrast with its limited expression in normal healthy individuals." (PMID 35986757, 2023). "In many cases, brain malignancies share common targetable tumor antigens and peptides with hematological cancers e.g. B7-H3, CD70, etc.." (PMID 36721153, 2023). "Lastly, several CD70-targeting agents have been investigated in CD70-expressing tumor indications and hematological malignancies, including anti-CD70 mAbs, ADCs and CAR T-cell therapy." (PMID 37345056, 2023). "This is due to the fact that CD70 expression patterns in patients varies among the different tumor types in spatial and temporal distribution, magnitude of expression and percentage of positive cells." (PMID 37093350, 2023). "Our observations showed that CD70 and CD274 are co-associated with IFNγ expression and are predominantly expressed in different immune cell types within the tumor microenvironment." (PMID 37106127, 2023). "In this way, investigations on animal models of GB, ovarian, and pancreatic cancers have shown that natural or ionizing radiation provokes tumor release of IL-8, which enhances the trafficking of IL-8 receptor-engineered CD-70-CAR T-cells to the tumor site." (PMID 37020537, 2023). "BLI images showed that treatment with CD70-CAR-T cells significantly reduced tumor burden of liver, spleen, and BM compared with control treatments, but failed to eliminate leukemic cells in lung." (PMID 36845088, 2023). "In the organoid-PBMC co-culture system, both anti-CD70 monotherapy and anti-PD-1 monotherapy significantly increased tumor cell death, but combination therapy exhibited greater tumor-killing efficacy in terms of the organoid number, size, and viability." (PMID 37024479, 2023).
tumor (continued). "We further examined CD70 expression on NPC cells isolated from fresh endoscopic biopsies via flow cytometry, showing that approximately 60% of EPCAM+ tumor cells were CD70+, whereas only 10% CD70+ cells in EPCAM- infiltrating immune/stromal cells." (PMID 37024479, 2023). "Immune evasion of malignant cells is closely associated with high CD70 expression, and overall survival of patients with CD70-expressing tumor cells is significantly reduced." (PMID 37139482, 2023). "Blocking CD70 with antagonistic antibodies greatly reduces Raji cell stimulation of non-tumor challenged HIS T cells treated with anti-CD3/CD28 in vitro." (PMID 37087494, 2023). "IgG1 was prioritized while developing anti-CD70 therapeutic antibodies since it has a high affinity for binding and activating FcγRs and can elicit potent ADCC and ADCP against CD70+ tumor cells." (PMID 37849799, 2023). "To better estimate the proliferation ability of CAR-T cells upon tumor challenge, we co-cultured anti-CD70 CAR-T and control T cells with three AML cells lines after being labeled with CFSE at an E:T ratio of 1:2." (PMID 36845088, 2023). "CD70 overexpression on tumor cells in multiple hematological malignancies and solid tumors has been therapeutically exploited preclinically and clinically as cancer-specific target." (PMID 37093350, 2023). "The evidence of degranulation and secretion of immune-effective cytokines collectively proved that nb70CAR-T cells can be specifically activated by CD70-positive tumor cells." (PMID 36932256, 2023). "Anti-CD70+ anti-PD-1 therapy is evaluated in xenograft-derived organoids and humanized mice, exhibiting an improved tumor-killing efficacy." (PMID 37024479, 2023). "After 7 days of engraftment, tumour‐bearing mice were randomised to receive IgG, anti‐CD70 treatment (αCD70) alone, anti‐PD‐L1 treatment (αPD‐L1) alone, or αCD70/αPD‐L1 cotreatment for 2 weeks." (PMID 36471481, 2022). "CD70 is overexpressed in a variety of solid and hematological tumors and plays a role in tumor proliferation and evasion of immune surveillance." (PMID 36239354, 2022). "It was found that overexpression of CD70 on tumors can facilitate immune evasion through CD27 expression in tumor-infiltrating Tregs." (PMID 36239354, 2022). "An in vitro investigation of CD70-targeting CAR T-cells found that the administration of the modified T-cells resulted in T-cell activation, CD27 co-stimulation, and recognition and killing of CD70-positive tumor cell lines and primary tumor samples." (PMID 35565190, 2022). "Our findings suggest that CD70 can play a role in either tumour suppression or oncogenesis in DLBCL, likely via distinct immune evasion mechanisms, that is, impairing T cell priming or inducing T cell exhaustion." (PMID 36471481, 2022). "CD70 functions similarly to immune checkpoint proteins in that it allows tumor cells to evade the anti-tumor immune response." (PMID 36572780, 2022). "Another antigen that can be harnessed for the development of CAR T-cell therapy is CD70, a protein belonging to the tumor necrosis family, which mediates the interaction between B- and T-lymphocytes." (PMID 35565190, 2022). "It is therefore possible that sub-populations of RMC tumor cells expressing CD70 trigger hyperstimulation of B cells into a tumor-promoting, imbalanced antibody-producing plasma cell state, and in that way evade an effective immune response." (PMID 35837094, 2022). "BTLA and CD70 concentrations were found to be higher in cancers with tumor cells present in the peritoneal fluid (p = 0.04, p = 0.02, respectively)." (PMID 35204342, 2022). "Although ADCs targeting CD70 are a promising approach to mediate selective killing of the tumor cells, these agents rely on the extent of internalization, which can differ greatly among tumor types." (PMID 34991665, 2022).
tumor (continued). "Together, the scRNA‐seq data suggest that the tumour microenvironment in CD70‐high expression DLBCL seems to be more immunosuppressive, characterised with T‐cell exhaustion." (PMID 36471481, 2022). "Our study showed increased FoxP3 expression and higher CD4+/CD8+ ratios in CD27+ tumor infiltrating lymphocytes surrounding CD70+ tumor cells in NSCLC patients." (PMID 34991665, 2022). "Another mechanism by which CD70 expressing tumor cells can exert immune suppression is by regulating immunosuppressive myeloid cells, such as macrophages." (PMID 34991665, 2022). "Overexpression of HDAC5 is related with upregulated CD70, inducing growth suppression and apoptosis of tumor cells." (PMID 35585975, 2022). "High expression of the CD276 gene is thought to be associated with the development and metastasis of several cancers, and CD70 is involved in the survival of tumor cells and regulatory T cells through interaction with its ligand CD27." (PMID 35677427, 2022). "In non-Hodgkin’s lymphoma (NHL), CD70+ B cells induce Foxp3 expression in tumor-infiltrating CD4+ CD25– T cells with immunosuppressive activity." (PMID 36239354, 2022). "Significantly lower protein expression was observed in tumour cells from samples harbouring CD70 genetic alterations (n = 15) compared with those with WT CD70 (n = 35)." (PMID 36471481, 2022). "CD70 is highly expressed in HNSCC tumor biopsies (20%) and 75% of specimens showed high CD70 expression on tumor surface." (PMID 36338731, 2022). "Another target that is being evaluated for tumour‐directed CD47 blocking is CD70, with CD70 antibodies themselves already being pursued for the treatment of solid cancers." (PMID 35908284, 2022). "Here, the tumor cells expressed the ligands CD70 and CD80–CD86 that bind to their respective CD27 and CD28 receptors expressed on CD8+ T cells." (PMID 36180422, 2022). "Though its overexpression fails to rouse immune response, CD70 can still be used to indicate tumor cells.SGN-CD70A is a CD70-targeted antibody–drug conjugate." (PMID 35978433, 2022). "Similar things happened in tumor cells, in which an NLRandP3-mediated release of IL-18 would downregulate CD70 on tumor cells and generate immune escape." (PMID 35978433, 2022). "Over the past decades, the importance of CD70 on solid tumors has become clear whereby aberrant expression of CD70 on tumor cells has been reported on numerous types of solid tumors with varying expression levels." (PMID 34991665, 2022). "The role of CD70 reverse signaling in tumor progression has already been described in hematological malignancies but is rather undefined in solid tumors." (PMID 34991665, 2022). "Current CAR T cells targeting CLL-1 and CD70 demonstrated cytotoxicity to tumor cells and spared CD34+ stem cells, indicating the potency of clinical implications for these two CAR T-cell treatments." (PMID 35990606, 2022). "Based on the quantification of CD70 mRNA expression on tumour cells, we divided patients into high‐expression and low‐expression groups." (PMID 36471481, 2022). "Several studies have indicated that the pathway mediated by CD27 and its ligand CD70 was involved in tumor growth and induction of lymphoid apoptosis." (PMID 35677048, 2022). "CD70 was only highly expressed in PH027, and it was implicated in tumor cell and regulatory T-cell survival through interaction with its ligand." (PMID 35865544, 2022). "Anti-CD70 antibodies inhibited tumor growth and prolonged mice survival in models of CD70-positive B cell malignancies, providing the rationale for targeting CD70 with CAR-T cells." (PMID 35681499, 2022). "In solid tumors, only expression of CD70 is present on the tumor cells which can facilitate immune evasion through CD27 expression in the tumor microenvironment." (PMID 34991665, 2022). "To comprehensively explore the tumour microenvironment in DLBCLs expressing CD70, we reanalysed our recently published single‐cell RNA sequencing (scRNA‐seq) data on an independent Chinese DLBCL cohort." (PMID 36471481, 2022).
tumor (continued). "In a recent study, two CD70-CAR T constructs exhibited significant anti-tumor efficacy in vitro and in vivo, effectively eliminating AML cells and sparing normal hematopoietic stem cells, thereby avoiding potentially dangerous on-target/off-tumor toxicity." (PMID 36077703, 2022). "CD70 was expressed at high levels in 4 (19%) of the 21 tumour biopsies and was intensely expressed on the surface of tumour cells in 3 of the 4 samples." (PMID 36016159, 2022). "Upon the targeting of CD70-expressing tumor cells, CD27 expression on CAR-T cells was quickly downregulated, suggesting that chronic CD27 stimulation is potentially deleterious." (PMID 35053463, 2022). "A recent report suggested that CD70 expressed by CAFs supports tumour progression in solid cancers by facilitating cancer cell migration." (PMID 35332263, 2022). "Currently, only PD1/PD-L1, CD47/SIRPα, TIM3/Galectin-9, and CD70/CD27 checkpoints have been shown to interact with each other to regulate tumor proliferation in pairs." (PMID 36358792, 2022). "Taken together, patients in the CD70 gene‐altered group and high CD70 group had similar poor long‐term survival, but their tumours exhibited distinct molecular signatures, suggesting different underlying mechanisms." (PMID 36471481, 2022). "We also performed transcriptomic analysis on bulk tumour tissues as well as single‐cell samples, to study the impact of CD70 alterations in tumour microenvironment (TME)." (PMID 36471481, 2022). "We also performed transcriptomic analysis to explore the role of CD70 alterations in tumour microenvironment." (PMID 36471481, 2022). "We further propose that RMC has an immune landscape comparable to that of untreated RCCs, including heterogenous expression of the immune ligand CD70 within a sub-population of tumor cells." (PMID 35837094, 2022). "Only immature moDCs which were incubated with tumor cells treated with HT of 44 °C significantly upregulated CD70 at 24 h." (PMID 35565180, 2022). "Using bulk RNA-seq data from, we observed that CD70 mRNA is highly overexpressed in RMC tumor compared with adjacent normal tissue (log2 fold change = 7.724, p-value = 3.269e-23)." (PMID 35837094, 2022). "Expression of CD70 in tumor cells from various hematological and solid malignancies is more commonly associated with poor prognoses." (PMID 34204115, 2021). "Preferable survival of iTIL-high tumor seemed more obvious in the CD70-low group than in the CD70-high group." (PMID 35145909, 2021). "Chronic stimulation of CD27 by CD70 in chronic inflammation suppresses the immune response and, in the case of tumour cells expressing CD70, leads to differentiation of T lymphocytes into Treg cells." (PMID 34200219, 2021). "Among the TNFL members investigated, OX40L and CD70 displayed the weakest cytotoxic effect (30% and 24.5% tumor cell death, respectively)." (PMID 34484225, 2021). "Immunoreactivity for CD70 was semi-quantitatively scored according to the proportion of positive tumor cells." (PMID 35145909, 2021). "Our PPI network analysis also revealed a direct interaction between B7‐H3 and CD70, consistent with a previous report that B7‐H3 and CD70 were highly co‐expressed and up‐regulated in multiple tumor types." (PMID 34562306, 2021). "Anti-CD70 antibodies have demonstrated potent anti-tumor activity in a murine PDAC model overexpressing CD70 and good tolerability and preliminary anti-tumor activity in various CD70 positive advanced (non-pancreatic) solid cancers." (PMID 34439292, 2021). "The higher CAR T cell antitumor activity resulted in improved tumor regression and survival of mice compared to those treated with unmodified CD70-specific CAR T cells." (PMID 34113233, 2021). "To redirect the specificity of T cells towards both CD70 and B7-H3 simultaneously using a single CAR molecule, we generated a TanCAR: a bivalent CAR molecule that can target 2 tumor-associated antigens in a tandem structure." (PMID 32685008, 2020).
tumor (continued). "Several pre-clinical studies with differently designed CD70-specific CAR-T cells have shown robust anti-tumor response against CD70+ mouse models." (PMID 33176788, 2020). "Our study provided the evidence of enhanced anti-tumor efficacy of TanCAR-T cell against multiple cancers expressing CD70 and B7-H3 in vitro and vivo." (PMID 32685008, 2020). "The CD70 targeted CAR-T cells with binding moiety of CD70 specific scFv exhibit a higher affinity and antitumor effect against CD70+ tumor cells." (PMID 32685008, 2020). "More recently, reverse signaling via its ligand CD70 was shown to also enhance NK-cell effector functions and contribute to tumor immunosurveillance." (PMID 33335526, 2020). "Collectively, these in vivo experiments indicated that TanCAR-T cells improve the control of established xenografts of tumor expressing CD70 and/or B7-H3 target antigens." (PMID 32685008, 2020). "In follow-up analysis the specific anti-tumor effect of TanCAR-T cells, we served Fadu and K562 cells as CD70-/B7-H3+ and CD70-/B7-H3- control, respectively." (PMID 32685008, 2020). "CD70 exhibited different expression patterns between tumor tissues (8/8) and their EVs (5/8), depending on the patient sample." (PMID 33276608, 2020). "CD70+ cancer cells communicate with CD27+ tumor infiltrating lymphocytes and induce their apoptosis." (PMID 33287223, 2020). "To overcome these limitations of EpCAM, we decided to test CD147, CA9, and CD70 as potential tumor markers for ccRCC." (PMID 33276608, 2020). "Human tumor cell lines NCI-H460 or A375 uniformly expressing CD70 was used to detect the affinity of trCD27 and CD70 specific scFv by immunofluorescence." (PMID 32685008, 2020). "CD70 positivity was found in 37 MCL samples (57%), of which 26 samples (70%) displayed CD70 expression on >50% of the tumour cells." (PMID 31652572, 2019). "Two papers published in 2017 reported that CD70-targeted CAR-T therapies confer strong anti-tumor responses in human cancer cells and animal models." (PMID 31752943, 2019). "Although CD70 positivity of the tumour cells is a prerequisite to enter solid tumour clinical trials while using anti-CD70 immunotherapy, there is currently no uniform IHC assay for evaluating CD70 expression." (PMID 31652572, 2019). "These discrepancies highlight the need for one uniform and validated methodology for stratifying tumour types for anti-CD70 immunotherapy." (PMID 31652572, 2019). "CD70 expression was assessed in 25 different solid tumour types (N = 496), which ranged from two to 101 samples per tumour type." (PMID 31652572, 2019). "Both anti-CD70 mAb and anti-CD70 antibody-drug conjugates (ADCs) have shown significant anti-tumor effects in xenograft models." (PMID 31186046, 2019). "In this retrospective study, we assessed the degree of CD70/CD27 expression across various tumour types while using one standardised and validated IHC assay." (PMID 31652572, 2019). "The variation in cut-off values to define CD70 expression also leads to inconsistent interpretations regarding CD70 expression profiles within identical tumour types." (PMID 31652572, 2019). "In our study, we compared CD70 expression in 496 solid tumour specimens while using one uniform CD70 IHC method, which allowed for us to compare CD70 expression within one specific neoplasm type as well as among different tumour types." (PMID 31652572, 2019). "The overexpression of CD70 on tumour cells has been described in multiple haematological malignancies and carcinomas." (PMID 31652572, 2019). "Of note, for some tumour types, the number of samples was too limited to significantly determine CD70 positivity and predict the benefit from anti-CD70 therapy." (PMID 31652572, 2019). "Our studies also indicate that CD70 is involved in macrophage tumor-infiltration and induction of CD8+ T-cell death in GBM9,24." (PMID 31488817, 2019).